CD36 (CD36 molecule (CD36 blood group))
Diseases named in the same sentence as CD36 in open-access papers (continued):
Sharing a sentence is not in itself a finding about the gene and the disease.
cardiomyopathy (16 papers, 2005 to 2025). A disease of the heart muscle or myocardium proper. "Because of its rate-controlling role in myocardial fatty acid metabolism, CD36 has been implicated in dysregulated fatty acid and lipid metabolism in high fat diet-induced cardiomyopathy." (PMID 32493392, 2020). "CD36 has been associated with many processes such as scavenger receptor functions, lipid metabolism, fatty acid transport, angiogenesis, cardiomyopathy and TGF-β activation." (PMID 16171515, 2005). "The authors reported only one CD36 deficiency and cardiomyopathy case, observed for two years." (PMID 37239003, 2023). "Increased CD36 expression has been found on the cardiac sarcolemma of some lipotoxic cardiomyopathy models and in cardiomyocytes of DCM patients." (PMID 40427484, 2025). "This review summarizes the extensive knowledge of the contribution of CD36 to DM and its complications, including nephropathy, retinopathy, peripheral neuropathy, and cardiomyopathy." (PMID 32796572, 2020). "The inclusion of PDLIM3 exon 6 is predicted to result in nonsense-mediated decay in cardiomyopathy, while CD36 exon 11 inclusion should result in protein truncation (AltAnalyze)." (PMID 28098235, 2017). "However, FAT/CD36 is highly induced in cardiac lipotoxicity models, including age-induced murine cardiomyopathy and diabetic cardiomyopathy." (PMID 37233656, 2023). "The CD36-dependent mechanisms are important events in the pathogenesis of diabetic complications, such as nephropathy, retinopathy, neuropathy, and cardiomyopathy." (PMID 32796572, 2020). "CD36 may also contribute to accumulation of lipids within cardiac myocytes and hence cardiomyopathy in aged mice." (PMID 27698205, 2017). "CD36 and SCD were mainly upregulated in some cardiomyopathy- and metabolism-related pathways and downregulated in some immune- and metabolism-related pathways." (PMID 37415143, 2023). "Relating to the lipid metabolism, CD36, a vital free fatty acid (FFA) transporter mediating the majority of FFA uptake in cardiomyopathy, also showed a decrease in dRV in our results." (PMID 35865003, 2022). "We identified genes with alternative splicing profiles that were common to cardiomyopathy (PDLIM3, CD36, CLDND1, TTN, FAM126a, TLR4, and CD59)." (PMID 28098235, 2017). "Notably, CD36 and S100A10 displayed negative correlations in Vascular smooth muscle contraction, Basal cell carcinoma, and different types of cardiomyopathy, and positive correlations in Allograft rejection and Asthma, among others." (PMID 39660117, 2024).
heart failure (16 papers, 2014 to 2025). Inability of the heart to pump blood at an adequate rate to meet tissue metabolic requirements. "Tamoxifen-inducible cardiomyocyte-specific CD36 knockout mice exhibit rapid progression from compensated hypertrophy to heart failure." (PMID 37233656, 2023). "Animal studies conducted over the last two decades further clarified the function of FAT/CD36 in heart failure." (PMID 37233656, 2023). "Alterations in myocardial metabolic substrate have been related to heart failure and dilated cardiomyopathy and it is noteworthy that DCM patients show CD36 deficiency." (PMID 31782728, 2019). "Recent study showed that the genetic deletion of CD36 (CD36KO), which causes reduction in FA use with an increased reliance on glucose, accelerates the progression from compensated hypertrophy to heart failure." (PMID 30104639, 2018). "Here, we show the mechanisms by which CD36 deletion accelerates heart failure in response to pressure overload." (PMID 30104639, 2018). "In contrast to end-stage HCM, cardiac CD36 protein and TG levels increased during pressure-overload-induced heart failure." (PMID 24567073, 2014). "Impaired synthesis of CD36 has been shown to shorten myocardial energy supply, resulting in insufficient fatty acid uptake and accumulation of toxic lipids, ultimately leading to heart failure." (PMID 38776872, 2024). "Several studies indicated that CD36 may contribute to cardiac dysfunction and heart failure in metabolic disorders with an inflammatory background; the factors regulating CD36 expression were well studied." (PMID 34881240, 2021). "Nuclear hormone receptor PPARα, and fatty acid receptor CD36 which play a critical role in FA metabolism in the heart, especially when the heart is stressed or in heart failure, were decreased in left ventricle of chronic ritonavir-treated animals by ~40% and ~64%, respectively." (PMID 29691457, 2018). "During heart failure development, Apo F increased in an attempt to protect the myocardium by activating LXR/RXR signaling through CD36 and PPARγ activation." (PMID 30132266, 2018). "Similarly, patients with heart failure have decreased FAT/CD36 and overall FA content, whereas FAT/CD36 gene expression is elevated after left ventricular assist device implantation, although the FA content remained unchanged." (PMID 37233656, 2023). "Furthermore, a combination of the potential therapeutic components (trimetazidine, CD36 inhibitors, MCD inhibitors, PDK inhibitors), targeting both fatty acid and glucose oxidation during heart failure could potentially restore metabolic inflexibility and improve cardiac function in heart failure." (PMID 29928647, 2018).
oral squamous cell carcinoma (16 papers, 2019 to 2026). "Here, we found that the FA transporter CD36 was upregulated in myofibroblastic cancer-associated fibroblasts (myoCAFs), where it correlated with the metastasis of oral squamous cell carcinoma (OSCC)." (PMID 42227941, 2026). "Our previous research demonstrated the involvement of CD36 in the proliferation and migration of oral squamous cell carcinoma (OSCC) cells." (PMID 41465497, 2025). "Further evidence establishing the link between adipocytes and cancer, CD36+ oral squamous cell carcinoma stimulated by high-fed diet or adipocyte-cultured medium strongly elevated pro-metastatic potential." (PMID 36428985, 2022). "Increasing literature demonstrates that overexpression of CD36 in cell lines of cervical and oral squamous cell carcinoma significantly increases their metastatic potential in vivo." (PMID 34215227, 2021). "For example, analysis of CD36+ cells showed that EMT-associated genes were expressed at lower levels in primary lesions and lymph node metastases in cases of oral squamous cell carcinoma." (PMID 33232276, 2020). "For instance, CD36 was reported in 2017 as the first molecular marker specific for tumor invasion and metastasis in oral squamous cell carcinoma." (PMID 33232276, 2020). "We have recently demonstrated that health-associated oral bacteria Streptococcus mitis, Neisseria flavescens, and Haemophilus parainfluenzae induce cytotoxicity in oral squamous cell carcinoma (OSCC) cell lines and downregulate CD36, a cancer-assocaited gene." (PMID 35600164, 2022). "More specifically, repeated injections of the anti-CD36 antibody (clone FA6–152) significantly attenuated the metastasis of oral squamous cell carcinoma without effect on the primary tumor." (PMID 34215227, 2021).
viral infection (16 papers, 2016 to 2025). "The viral infection stimulates alveolar macrophages to adopt an inflammatory phenotype regulated, at least in part, by the cluster of differentiation 36 receptor (CD36) to produce unrestrained inflammatory cytokine secretions." (PMID 38384295, 2024). "NRF2 induces the expression of genes that promote specificity of macrophages such as the macrophage receptor, which is responsible for bacterial phagocytosis, and the cluster of differentiation gene 36 (CD36), which resists viral infection." (PMID 37007526, 2023). "Here we show that activated NK cells increase the expression of the FA uptake receptor CD36 and subsequently the uptake of FAs upon acute virus infection." (PMID 38094304, 2023). "The aim of this study was to investigate the role of CD36 in the effects of viral infection on macrophage phagocytic function." (PMID 27701435, 2016). "In summary, we have shown that whilst viral infection and IFNβ treatment of macrophages downregulates both phagocytic ability and CD36 expression, the downregulation of CD36 appears to be uncoupled from bacterial phagocytosis." (PMID 27701435, 2016). "To ascertain whether the attenuated virus infection in RBP4-deficient cells was due to lower levels of CD36, we investigated the impact of SA expression in these cells through CD36 overexpression." (PMID 41144502, 2025). "Furthermore, in human microvascular ECs, the expression of the FA transporter CD36 increased in response to viral infection." (PMID 39119214, 2024). "Besides, phagocytosis or anti-viral activity-related genes (such as MSR1, CD36) or viral protein interactions with cytokine-cytokine receptors, were upregulated in iM2φ following viral infection." (PMID 35440562, 2022). "Also, Nrf2 induces tissue repair genes, anti-oxidative protein, CD36 as scavenger receptor, and IL-17D as protector against viral infections." (PMID 33743807, 2021). "Our data suggest no role for CD36, CD204 or CD206 in decreased bacterial uptake in response to viral infection." (PMID 27701435, 2016).
COVID-19 (15 papers, 2021 to 2025). A disease caused by infection with severe acute respiratory syndrome coronavirus 2. "Here, the authors show that the E protein are associated with coagulation disorders in COVID-19 patients and could directly enhance platelet activation and thrombosis through a CD36/p38 MAPK/NF-kB signaling axis." (PMID 37604832, 2023). "Consistently, the colocalization of the E protein and CD36 were identified on platelets isolated from COVID-19 patients." (PMID 37604832, 2023). "Analysis of the expression of RBC surface markers, such as CD235a and CD36, showed that SARS-CoV-2 was associated with significantly higher expression of these markers in COVID-19 patients." (PMID 35964959, 2022). "We found a reduction in the protein levels of CD36 in S1009+ infiltrating phagocytes in the lungs of COVID-19 patients compared to control tissues." (PMID 35666101, 2022). "Moreover, the E protein of SARS-CoV-2, which plays a central role in cytokine secretion and progression towards ARDS, was found to bind to CD36 and shown to be involved in COVID-19-induced thrombosis." (PMID 38384295, 2024). "Accordingly, CD36 has been proposed as target for severe COVID-19 patients." (PMID 38384295, 2024). "CD36 is differentially expressed in patients with COVID-19 and recovered individuals." (PMID 37109540, 2023). "Finally, the analysis of CD36 expression results showed increased expression of CD36 in the COVID-19 patients." (PMID 35964959, 2022). "CD36 expression was significantly different in COVID-19 than in healthy controls (p≤0.0001)." (PMID 35964959, 2022). "We hypothesized that upregulation of CD36 expression could be a predictive factor for severe COVID-19 with possible lethal outcomes." (PMID 34944005, 2021). "Our novel findings that CD36 (as well as other prominent signaling pathways) may be involved in the pathogenesis of COVID-19 has implications for host-directed therapy for SARS-CoV-2 infection." (PMID 33674719, 2021). "This may be because severe COVID-19 is characterized by a high frequency of classical monocyte subsets expressing CD36." (PMID 34944005, 2021). "Increased CD36 expression may therefore provide a protective role from an extreme lung injury during COVID-19, which is observed in the macaques." (PMID 33674719, 2021). "Furthermore, we found increased levels of CD36+ EVs in COVID-19 patients." (PMID 38069209, 2023). "All these results suggest that COVID-19 may alter CD36 gene expression." (PMID 37109540, 2023). "Finally, there are limited data on the expression of CD36 in COVID-19 patients." (PMID 35964959, 2022). "Together, our study reveals a critical role for the CD36-p38 axis in E protein-induced platelet hyperactivity, which could serve as an actionable target for developing therapies against aberrant thrombotic events related to the severity and mortality of COVID-19." (PMID 37604832, 2023). "Having shown that the RDW was elevated in the COVID-19 group, the expression of some RBC surface markers, such as CD235a, and CD36 was examined using flow cytometry." (PMID 35964959, 2022). "All genes (PPARG, CD36, STAB1, ITGAV, and ANXA2) downregulated in surviving patients with COVID-19 are related to cholesterol homeostasis." (PMID 34944005, 2021). "Thus, elevated CD36 and STAB1 gene expression may indicate increased oxidized lipoproteins uptake during severe COVID-19 and this in turn partially could explain lipid profile abnormalities observed in our study as well as in others." (PMID 36758022, 2023). "In summary, the expression patterns of CD36, GLUT2, IRS1, IRS2, PDX1, and PPARG in the pancreas were altered upon SARS-CoV-2 infection, implying that islet function may be compromised in patients with COVID-19." (PMID 35343389, 2022). "Of note, both the protein expression of CD36 and the phosphorylation of p38 MAPK and NF-κB were significantly upregulated in COVID-19 platelets with or without the presence of agonists." (PMID 37604832, 2023).
COVID-19 (continued). "In the COVID-19 patient without SARS-CoV-2 virus expression in the pancreas (SARS-CoV-2 negative), CD36, GLUT2, IRS2, and PDX1 were widely distributed in the pancreatic, serous acini, duct (exocrine gland) and islet (endocrine gland)." (PMID 35343389, 2022).
Sepsis (15 papers, 2012 to 2025). Sepsis is defined as life-threatening organ dysfunction caused by a dysregulated host response to infection. "In sepsis lipid metabolism is significantly dysregulated and this dysregulation has been associated with elevated levels of CD36, which contribute with the worsening of sepsis pathology, organ dysfunction and increased mortality." (PMID 40725160, 2025). "Given its involvement in sepsis pathogenesis, CD36 is currently considered an important target for sepsis treatment since the suppression of CD36 has been associated with ameliorated symptoms and improve survival outcomes." (PMID 40725160, 2025). "In addition, CD36 has been associated with metabolic diseases that present alterations in lipid metabolism and is upregulated in septic patients and sepsis animal models." (PMID 37600769, 2023). "In addition, sepsis was associated with increased mRNA abundance of the apical fatty acid transporter Cd36 with comparable induction in both genotypes." (PMID 23145105, 2012). "From these proteins, TNFα, IL-1α, Lck, NOS2, SOD2 and CD36 were selected for validation by Western blot on murine bone marrow-derived macrophages due to their relevant roles in the NF-κB, iNOS, oxidative stress, and phagosome signaling pathways, which are closely associated with sepsis pathogenesis." (PMID 40725160, 2025). "Furthermore, CD36 deficiency improved sepsis outcomes in mice." (PMID 37600769, 2023). "Gene expression of fatty acid uptake transporters Cd36 (Cd36) and Fatp1 (Slc27a1) increased with sepsis and stayed elevated during prolonged sepsis (2.2)." (PMID 39821755, 2025). "During sepsis-induced liver injury, LPS upregulates CD36 expression and facilitate the formation of CD36-UBQLN1-SNARE complex." (PMID 40461967, 2025). "Nevertheless, hepatic and muscular Cd36 gene expression were still higher with sepsis, for liver only in overweight/obese mice." (PMID 31262340, 2019). "In recent experiments in our laboratory, CD36 expression was increased in skeletal muscle during sepsis and treatment of cultured myotubes with dexamethasone resulted in increased expression of CD36 and FATP1 (unpublished observations)." (PMID 23555761, 2013). "Therefore, the observation that Fh15 significantly downregulate CD36 represents one of the most relevant findings of our study and reinforce the potential of Fh15 as biotherapeutic against sepsis." (PMID 40725160, 2025). "Indeed, sepsis-induced upregulation of fatty acid uptake transporter Cd36 mRNA in muscle and liver was most pronounced in the overweight/obese." (PMID 31262340, 2019). "Recently, the role of SR-Bs in sepsis has been increasingly investigated, and several studies using SR-BI/-BII- and CD36-knockout mice demonstrated their protective role in cecal ligation and puncture (CLP)-induced sepsis and endotoxemia." (PMID 39125954, 2024). "For example, the outgoing signaling of C1_CD36, C3_B, C9_STOM, and C10_ULK1 cells was dominated by “pattern 1,” which included RESISTIN and VISFATIN in sepsis." (PMID 37919720, 2023). "Here, we show that TLR2, TLR4, CD36, P2RX7, VIMP, and SCARB1 are also expressed in myocytes and muscle and that muscular expression of TLR2, TLR4, CD36, and VIMP increases during sepsis." (PMID 31441598, 2020). "Decreased expression of CD69, CD36 (DE 1.78 and −5.53 respectively at 18 h) and MHC II genes (H2-OB) in peritoneal cell profiles is consistent with the blood profiles of sepsis patients at late stages of sepsis." (PMID 23009705, 2012). "Following treatment with TREM2-Fc protein, the expressions of CD36, CPTI, and CPTII in monocytes were increased in sepsis patients but not in healthy controls, indicating an enhancement of FAO after TREM2 blockade during sepsis." (PMID 39405126, 2024).
chronic kidney disease (14 papers, 2016 to 2025). Impairment of the renal function secondary to chronic kidney damage persisting for three or more months. "Patients with chronic kidney disease, particularly those with diabetic nephropathy, show increased CD36 expression." (PMID 40625574, 2023). "We provide evidence that AOPP-albumin isolated from end stage renal disease patients as well as in vitro generated AOPPs markedly increase ADP-induced platelet aggregation via CD36." (PMID 26905525, 2016). "During chronic kidney disease, CD36 expression is elevated, and the phagocytosis of apoptotic cells driven by CD36 could be a crucial route for fibrosis advancement." (PMID 40046045, 2025). "Importantly, high renal levels of CD36 have been found in patients with chronic kidney disease (CKD) and CD36 has been proposed to play a central role in CKD development." (PMID 37955868, 2024). "This is supported by renal disease; patients with proteinuria have higher levels of CD36 expression in the renal proximal convoluted tubule, while treatment of mice with induced chronic kidney disease with the CD36 inhibitor 5A peptide reduces interstitial fibrosis." (PMID 37593175, 2023). "On the other hand, CD36, encoding a multifunctional receptor that mediates the binding and cellular uptake of long-chain fatty acids, was greatly upregulated (12.3×), consistent with the upregulation of CD36 in the setting of chronic kidney disease (CKD)." (PMID 39000280, 2024). "CD36 is expressed in tubular epithelial cells and it affects kidney lipid metabolism as well as the binding and uptake of albumin in the proximal tubule, is significantly upregulated in chronic kidney disease (CKD), and it plays a significant role both in the diagnosis and therapy of renal fibrosis." (PMID 35713363, 2022). "Numerous studies have shown that CD36 participates in the pathogenesis of several kinds of chronic kidney disease (CKD)." (PMID 31592160, 2019). "Renal CD36 is mainly expressed in the proximal tubule cells, podocytes, and mesangial cells, and is markedly upregulated in the setting of chronic kidney disease (CKD)." (PMID 30934807, 2019).